BUB1B (BUB1 mitotic checkpoint serine/threonine kinase B)
Diseases named in the same sentence as BUB1B in open-access papers (continued):
Sharing a sentence is not in itself a finding about the gene and the disease.
tumor (148 papers, 2009 to 2025). "The results revealed that a higher expression of BUB1B in OC tissues was associated with a higher proportion of tumor cells; moreover, infiltration of CD4 T+ cells, macrophages, and neutrophils also showed an increasing trend." (PMID 41163302, 2025). "Our findings indicated that the expression of BUB1B was positively correlated with the infiltration levels of MDSCs across various tumor types, with the most pronounced associations observed in ACC, LIHC, KICH, and LUAD." (PMID 40076684, 2025). "Our findings indicate that BUB1B exhibits a positive association with cell cycle and proliferation across the majority of tumor types." (PMID 40076684, 2025). "We discovered that the majority of the 38 immune cell subtypes are significantly linked with BUB1B expression in various tumor types using the deconvo xCell method." (PMID 37055476, 2023). "BUB1B mutation not only correlated with tumor progression but also was detrimental to woman's health." (PMID 35517426, 2022). "DLGAP5 has been reported to be correlated with clinical prognosis, immune cell infiltration, and tumor mutational burden across multiple tumors in previous studies; thus, BUB1B was chosen for further analysis." (PMID 36185088, 2022). "In DLBC, high expression of BUB1B was found to be associated with higher tumor stage (Stage1 vs 2, p=0.038; Stage1 vs 4, p=0.024." (PMID 35847923, 2022). "BUB1 and BUB1B suppress the immune response by increasing the expression of immune checkpoint molecules, causing tumor cells to form immune escape." (PMID 35493295, 2022). "The phosphorylated protein-chip results showed that the knockdown of BUB1B suppressed the expressions of a series of proteins associated with tumor growth and invasiveness." (PMID 33431813, 2021). "It has been reported that the loss of acetylation of the Bub1b results in defects in spindle assembly checkpoint signaling and promotes tumor formation." (PMID 32977361, 2020). "We observed that high levels of BUB1B were significantly associated with larger tumor size, multiple tumors and microvascular invasion, and higher TNM and Edmonson stages." (PMID 32977361, 2020). "Encoded by BUB1B, high expression of the BUBR1 was correlated with larger tumor size, higher histological grade, advanced pathological stage, and poor survival in HCC patients, which is in line with our results." (PMID 30363964, 2018). "Of the 78 available sequenced tumor samples, we found increases in the mutation frequency of all 3 of these genes: BUB1B increased from 2 to 7% of patients, PINK1 from 1 to 7% of patients, and COL16A1 from 4 to 11% of patients." (PMID 28173755, 2017). "An additional 4-month exposure to the BRAF inhibitor vemurafenib resulted in a highly drug resistant tumor that showed 3 additional new DNA mutations in the genes BUB1B, PINK1, and COL16A1." (PMID 28173755, 2017). "We can not, however, exclude the possibility that germline polymorphisms in the mitotic checkpoint genes AURKA and BUB1B, despite being heterozygous, facilitated tumour formation." (PMID 26102504, 2015). "Also, LUAD tumor tissues with high expression of BUB1b had a higher risk of lymph node metastasis and TNM III–IV stage." (PMID 39043653, 2024). "Furthermore, we identified eight hub genes (VSNL1, TH, PCP4, IGDCC3, RAD51AP2, MUC2, BUB1, and BUB1B) that promoted tumor progression and were associated with prognosis according to the Kaplan–Meier and ROC curve analyses." (PMID 36979826, 2023). "Interestingly, a strong association between the expression of BUB1B and the majority of immunosuppressive as well as immunostimulatory molecules in various tumor types was also looked at in this study." (PMID 37055476, 2023). "It followed that BUB1B mutation was significantly related to tumor development." (PMID 35517426, 2022). "Apart from abnormal expression and mutation, polymorphisms in BUB1B may contribute to tumorigenesis and the risk of tumor development." (PMID 35517426, 2022).
tumor (continued). "Therefore, TOP2A, NCAPG, and BUB1B are possible prognostic indicators associated with tumor-infiltrating immune cells in the tumor microenvironment." (PMID 36245843, 2022). "Based on the results from the experiments that indicate mutagenic NHEJ with increased BUB1B/BUBR1 expression, we hypothesized that BC tumor with aberrant BUB1B/BUBR1 expression level harbors higher mutation counts." (PMID 34545188, 2021). "BUB1B may contribute to gastric tumorigenesis and the risk of tumor development." (PMID 29246203, 2017). "The results showed that BUB1B expression was significantly greater in tumour tissues than in adjacent normal tissues." (PMID 40857057, 2025). "Taken together, our results demonstrated that YY2 promotes the formation of micronuclei and the release of dsDNA by enhancing BUB1B expression and chromosome missegregation, thereby inducing pyroptosis and the development of a tumor immune microenvironment." (PMID 39903759, 2025). "Following BUB1B knockdown, cell proliferation, migration, invasion, and tumor growth and metastasis were suppressed in vitro and in vivo." (PMID 41163302, 2025). "qRT‐PCR and western blot assays revealed that BUB1B expression in tumor tissues was significantly reduced by BUB1B knockdown." (PMID 41163302, 2025). "We also investigated the correlation between BUB1B expression levels and the tumor microenvironment (TME), including the expression of immunomodulators and the infiltration of immune cells." (PMID 40076684, 2025). "BUB1B knockdown inhibited OC cell proliferation, migration, invasion, and tumor growth via the Wnt/β‐catenin signaling pathway, indicating the potential therapeutic value of BUB1B for OC." (PMID 41163302, 2025). "For example, the overexpression of BUB1 and BUB1B promotes tumor cell proliferation and metastasis by interfering with spindle assembly checkpoints in mitosis, while the knockdown of BUB1B inhibits cell proliferation, invasion, and migration in vitro." (PMID 39940833, 2025). "These efforts aim to enhance the understanding of the significance and potential role of BUB1B across various tumor types." (PMID 40076684, 2025). "The bioinformatic results and immunohistochemistry (IHC) staining of BUB1b in a tissue microarray showed that BUB1b was significantly elevated in tumor tissues in contrast to normal tissues, and LUAD patients with high BUB1b expression had a dismal prognosis." (PMID 39043653, 2024). "We also verified the potential role of BUB1b in chemotherapy via the IHC staining of BUB1b in tumor tissues of LUAD patients accepting neoadjuvant chemotherapy." (PMID 39043653, 2024). "The silencing of BUB1b significantly retarded subcutaneous tumor growth and improved survival, while the overexpression of BUB1b accelerated tumor growth and shortened survival." (PMID 39043653, 2024). "The bioinformatics analysis of the GEPIA2 database suggested that BUB1b was highly expressed in the tumor tissues of LUAD compared with normal tissues." (PMID 39043653, 2024). "We first confirmed aberrantly highly expressed BUB1b in LUAD tumor tissues compared to normal or para-tumor tissues, which was an independent predictor for a dismal prognosis." (PMID 39043653, 2024). "Here we found that both the transcript and protein levels of BUB1b were dramatically upregulated in tumor tissues and contributed to the dismal prognosis of LUAD patients." (PMID 39043653, 2024). "Multiple research works have confirmed that abnormal BUB1B expression is related to tumor prognosis." (PMID 37808164, 2023). "We calculated immune infiltration scores for a total of 10,178 tumor samples from 44 tumor types, and Spearman’s correlation coefficient was determined between the levels of immune infiltration and BUB1B expression using corr." (PMID 37055476, 2023). "Previous study indicated tumor implantation in mice showed that inhibition of BUB1B reduced tumor volumes by approximately 30% in two independent cohorts." (PMID 37228122, 2023).
tumor (continued). "So BUB1B high expression on HCC patients related to changes in the immune-related tumor microenvironment and also to immunotherapy." (PMID 36829489, 2023). "The Spearman correlation for each tumor was evaluated, and BUB1B interacts with RNAss and DNAss to varied degrees." (PMID 37055476, 2023). "This study found that BUB1B was significantly upregulated in multiple tumors across both paired (18 tumor types) and unpaired (33 tumor types) sample analyses, which is consistent with the literature." (PMID 37055476, 2023). "BUB1B, also known as BUBR1, is a functional protein at the checkpoint, which contributes to tumor development and progression." (PMID 37853361, 2023). "BUB1 and BUB1B mediate apoptosis in response to chromosomal aberration and inhibit the proliferation and metastasis of tumor cells." (PMID 36979826, 2023). "BRCA1-A and BUB1B belong to core elements of the spindle assembly checkpoint (SAC) correlated with tumor progression, worse OS and DFS in HCC." (PMID 37968735, 2023). "The link between BUB1B expression and tumor stemness, as determined by RNAss and DNAss, was examined in the current study." (PMID 37055476, 2023). "The upregulation of BUB1B in tumor tissues are related to worse OS and disease-free survival (DFS) in PDAC." (PMID 36741321, 2023). "Given that, we assume that high expression of BUB1B decreased both the immune cell and stromal cell infiltration but increased the number of tumor cells, which leads to a bad prognosis." (PMID 37055476, 2023). "Knocking-out BUB1B resulted in suppression of cell proliferation, migration, and invasion in vitro, and inhibition of tumor growth in the xenograft experiment." (PMID 35068350, 2022). "BUB1 and BUB1B inhibit the immune response by increasing the expression of immune checkpoint molecules, resulting in immune escape of tumor cells, which is conducive to the occurrence and development of BrCa." (PMID 35493295, 2022). "The average tumor volume and weight was lower in the BUB1B-knockdown group compared to that in the control group." (PMID 35068350, 2022). "BUB1B was reported to be involved in tumor cell cycle regulation, and overexpression of BUB1B is related to the progression and recurrence of HCC." (PMID 36317111, 2022). "These researches suggested the importance of BUB1B in tumor progression and significant prognostic value on patient survival." (PMID 35517426, 2022). "Meanwhile, we also found that BUB3 can negatively regulate B lymphocytes, and BUB1 and BUB1B inhibit immune responses by promoting the secretion level of checkpoint molecules of the immune system, leading to immune escape of tumor cells." (PMID 35493295, 2022). "BUB1B is not only a key component of the spindle assembly checkpoint, but its abnormal expression usually represents a poor prognosis of the tumor." (PMID 35860256, 2022). "We further found that BUB1B was essential for tumor cell proliferation, and BUB1B high expression predicted a shorter PFS time of THCA patients." (PMID 35517426, 2022). "In line with the mRNA analysis, the BUB1B protein abundance is correlated with the tumor stage, recurrence rate, and distant metastasis in LUAD patients." (PMID 35068350, 2022). "Similar to the expression file in ECC, the expression of BUB1B was also increased in ICC tissues with their corresponding para-tumor tissues." (PMID 33431813, 2021). "Our results showed that the knockdown of BUB1B was able to significantly suppress tumorigenicity, resulting in obvious reductions in tumor weight and volume compared to the control group." (PMID 33431813, 2021). "Taken together, our research suggested that BUB1B positively regulated the JNK/c-Jun signaling pathway to exert its tumor-promoted functions in CCA." (PMID 33431813, 2021). "The up-regulation of BUB1B in tumor tissues of patients with HCC predicts poor OS and relapse-free survival (RFS), which is consistent with our results." (PMID 34257537, 2021).
tumor (continued). "The results showed that the expression level of BUB1B was upregulated in ECC tissues compared with their corresponding para-tumor tissues." (PMID 33431813, 2021). "Most importantly, targeting BUB1B and circBUB1B_544aa by siRNA significantly inhibited tumor growth in NOD-SCID mice." (PMID 34620840, 2021). "In fact, several studies have showed that BUB1B promote tumor growth and metastasis in many solid tumors." (PMID 34646769, 2021). "To extend our findings into antimitotic chemotherapy response, we investigated the FOXM1-dependent co-regulation of BMF and BUB1B expression in the context of tumor cell treatment." (PMID 34035233, 2021). "CENPF, BUB1, BUB1B, KIF23 and TTK were identified as the key potential genes affecting hypoxia associated tumor stemness in this study." (PMID 33148251, 2020). "We generated subcutaneous xenograft tumor mouse models of HCC to further examine the effect of BUB1B on tumor progression." (PMID 32977361, 2020). "By collecting and analyzing clinical data, we discovered that the expression of BUB1B was closely correlated with worse clinicopathologic features, including larger tumor size, multiple tumors, microvascular invasion, and higher TNM and Edmonson stages." (PMID 32977361, 2020). "In conclusion, the up-regulation of BUB1B, CCNA2, CDC20, CDK1, and WEE1 in tumor tissues are associated with worse OS and DFS in PDAC and is correlated with advanced tumor stage and tumor development." (PMID 30765611, 2019). "CTLA4, MZB1, NIP7, and BUB1B in ADC, as well as GNG11 and CCNB2 in SCC, are novel top hub genes in modules associated with tumour size, SUVmax, and recurrence-free survival." (PMID 31877723, 2019). "Using FISH analysis, mice expressing the various Bub1b mutant transgenes revealed that tumor protection tightly correlated with an ability to counteract KrasG12D-mediated aneuploidization." (PMID 27528194, 2016). "To better understand the role of BUB1B in tumor metastasis, we asked which step(s) during this process was impacted by BUB1B expression." (PMID 26000094, 2015). "In allograft and tail vein mouse model studies, BUB1B suppression inhibited primary tumor growth and reduced metastasis to the lung and lymph nodes, resulting in prolonged survival in both tumor prevention and tumor intervention settings." (PMID 26000094, 2015). "In the tumor intervention setting, BUB1B knockdown was initiated 16 days after LKPH2 cell injection, a time when systemic tumors were well established." (PMID 26000094, 2015). "In the tumor prevention setting, BUB1B knockdown was initiated at the time of injection of LKPH2 cells." (PMID 26000094, 2015). "Several reports have shown that knockdown of BUB1B significantly reduced the viability of tumor cells and genetically transformed cells in 2D culture by triggering lethal chromosomal instability." (PMID 26000094, 2015). "Mice implanted with cell lines in which BUB1B expression was knocked down by RNAi exhibited reductions in primary tumor growth and metastasis to distant sites as well as prolonged overall survival." (PMID 26000094, 2015). "At the end of study (day 20), BUB1B levels remained substantially reduced (~60-70%), which correlated with a modest reduction in primary tumor growth." (PMID 26000094, 2015). "TOP2A and MCM2 immunostaining was localized to the nuclei of the tumor cells and benign mammary epithelium, while BUB1B protein immunostaining was cytoplasmic, as has been demonstrated in a variety of normal human tissues." (PMID 21785684, 2011). "BUB1B, a member of the spindle assembly checkpoint family known as BUB1 mitotic checkpoint serine/threonine kinase B, has been associated with the promotion of tumor progression." (PMID 40076684, 2025). "Thus, in vivo experiments confirmed that KIFC1 regulates BUB1B and the downstream Wnt/β‐catenin pathway, promoting tumour growth." (PMID 40857057, 2025).
tumor (continued). "Syngeneic graft experiments with MC38 cells overexpressing YY2 showed that BUB1B knockdown abolished the YY2 tumor suppressive effect, as well as its positive impact on chromosome missegregation, caspase‐1/GSDMD activation, IL‐1β, and cell death rate in syngeneic graft lesions." (PMID 39903759, 2025). "In addition, BUB1B knockdown ameliorated the malignant behavior of OC and led to smaller OC tumor volume and weight in nude mice." (PMID 41163302, 2025). "Additionally, the GEPIA database revealed high expression of BUB1B in patients with tumours, which adversely affected patient prognosis." (PMID 40857057, 2025). "Consequently, the level of BUB1b was significantly higher in tumor tissues of LUAD patients that had poor response to chemotherapy." (PMID 39043653, 2024). "Consistently, both the mRNA and protein levels of BUB1b were obviously elevated in tumor tissues." (PMID 39043653, 2024). "We further investigated the roles of BUB1 and BUB1B in Ishikawa cells using siRNA and found that silencing BUB1 and BUB1B inhibited cell proliferation, migration and invasion, indicating that BUB1 and BUB1B may exhibit tumor-promoting functions in EC." (PMID 39048649, 2024). "However, the function of BUB1B and its impact on the tumor immune milieu have received little attention so far." (PMID 37055476, 2023). "In the case of GBM, BUB1B was found to promote tumor proliferation." (PMID 36900109, 2023). "BUB1B is an important factor for tumor cell growth, proliferation and metastasis." (PMID 37228122, 2023). "Using the TCGA database, we investigated the oncogenic function of BUB1B in 33 tumor types." (PMID 37055476, 2023). "The present findings show a close relationship between BUB1B and the tumor immunological environment, implying that BUB1B could be a promising research and therapeutic target, however, further validation trials are required." (PMID 37055476, 2023). "Knockdown of BUB1B has been shown to reduce tumor growth in vivo." (PMID 35847923, 2022). "Knockout of BUB1B on the mouse MDA-MB-468 cell line can reduce tumor growth." (PMID 35493295, 2022). "Additionally, BUB1B is important in initiating apoptosis in polyploid cells that retreat abnormally from mitotic stasis, a process that contributes to tumor suppression." (PMID 35493295, 2022). "It followed that BUB1B significantly participated in the tumor progression." (PMID 35517426, 2022). "Meanwhile, the gene of Bub1b was the essential component of the mitotic checkpoint, which may play a role for tumor suppression." (PMID 35387338, 2022). "Significantly, knocking-down BUB1B suppressed LUAD tumor growth in a xenograft model." (PMID 35068350, 2022). "Taken together, our data suggest that BUB1B can promote tumor progression and metastasis in vivo." (PMID 32977361, 2020). "In addition, PDAC patients with neoplasms of histologic grade G3-4 had significantly higher BUB1B, CCNA2 and CDC20 levels (all P<0.05)." (PMID 30765611, 2019). "Moreover, overexpression of BUB1B, CCNA2, CDC20, and CDK1 in tumor tissues was significantly associated with disease-free survival (DFS) in PDAC patients (Log rank P=0.00565, P=0.0357, P=0.00104, and P=0.00121, respectively)." (PMID 30765611, 2019). "In contrast, Bub1bΔI fully retained the tumor-protective benefit of FL-Bub1b." (PMID 27528194, 2016). "Cell cycle profiles and more detailed analyses to pinpoint the exact sequences and associated signaling pathways for cells grown under anchorage-independent conditions are needed to delineate the mechanisms by which BUB1B functions under these conditions and during tumor metastasis." (PMID 26000094, 2015). "Mechanistically, little is known regarding how increased BUB1B expression may contribute to tumor progression." (PMID 26000094, 2015). "Thus, BUB1B participates in reshaping the tumor immune environment." (PMID 41163302, 2025).